CAT (catalase)
Diseases named in the same sentence as CAT in open-access papers (continued):
Sharing a sentence is not in itself a finding about the gene and the disease.
tumor (continued). "Furthermore, the activity of antioxidant systems, including superoxide dismutase (SOD), catalase (CAT), and glutathione (GSH), is significantly higher in normal cells compared to tumor cells." (PMID 41514605, 2025). "SUN EPS dramatically reduced SOD activity by 76%, ROS by more than 50%, and CAT activity by 34%, showing that EPS may prevent tumor cell development rather than destroy tumor cells." (PMID 41311846, 2025). "Among the genes, ACTG1, CAT, and RAF1 were upregulated in tumor tissues relative to normal tissues." (PMID 38806963, 2024). "In addition, overexpression of extracellular and intracellular Catalase but not SOD reduces Idgf3 induction via JNK, similar to the feedback loop that has been identified in other tumor models." (PMID 37188187, 2023). "Moreover, the expression levels of the CAT, ESR1, and KLKB1 genes were significantly correlated with the HCC stage (P < 0.05), while MMP9 was not significantly correlated with the tumor stage." (PMID 34671598, 2021). "In addition, the level of GSH and the activities of SOD, GPx, and CAT in hippocampus of the groups treated with DOX were significantly lower than those of the NC group (P < 0.01), and the tumor did not have remark effect on these enzyme activities." (PMID 34234834, 2021). "In our previous work, we showed that serum catalase (CAT) and plasma malondialdehyde (MDA) may be potential non-invasive biomarkers indicating tumour invasion depth or the presence of lymph node metastasis." (PMID 32575703, 2020). "Thus EASA treatment resulted in amelioration of tumor-induced oxidative stress by multiple mechanisms, involving modulation of lipid peroxidation, endogenous non-enzymatic (GSH) and enzymatic (SOD, CAT) antioxidant systems." (PMID 27486371, 2015). "Finally, in a short-term B cell acute lymphoblastic leukemia (B-ALL) mouse model showing incomplete tumor control, we also observed significantly reduced CD19 expression on tumor cells from mice treated with FMC63 CAR T cells but not CAT CAR T cells." (PMID 35490197, 2022). "In addition, we observed the increased activity of metalloproteinases (MMP-2 and MMP-12) and levels of the tumor angiogenesis marker VEFG and the lipid peroxidation marker MDA, as well as decreased levels of the non-enzymatic antioxidant GSH and enzymatic antioxidants CAT and GSH-Px in lung tissues." (PMID 31842482, 2019).
cancer (536 papers, 1999 to 2026). A tumor composed of atypical neoplastic, often pleomorphic cells that invade other tissues. "Catalase, a key peroxisomal ROS controller, is implicated in various cancers, as cancer cells often reduce ROS levels to avoid apoptosis." (PMID 40229252, 2025). "While higher catalase activity has been associated with a less aggressive cancer phenotype and reduced metastatic potential, its reduction here suggests a weakened antioxidant defense." (PMID 39767718, 2024). "Given this ubiquitous role, CAT activity has been linked to inflammation, cell death, aging, and cancer." (PMID 37839702, 2023). "It has been suggested that the anticancer effect of AA is through H2O2 accumulation due to CAT deficiency in cancer cells and subsequent cell death by apoptosis, pyknosis, and necrosis and through the nuclear translocation of an apoptosis-inducing factor." (PMID 36830015, 2023). "Emerging evidence reveals that membrane-associated CAT imparts resistance and favors the growth of cancer cells." (PMID 36307808, 2022). "CAT is localized to peroxisomes and cytoplasm and is implicated in ethanol metabolism, inflammation, apoptosis, aging and cancer." (PMID 36496858, 2022). "Silenced CAT expression increased the susceptibility of the cancer cell line BT-20 to oxidative stress." (PMID 36467027, 2022). "For example, polymorphism in the catalase-encoding gene resulted in oxidative DNA damage, the subsequent risk of cancer susceptibility, and the development of the mental disorder." (PMID 35453573, 2022). "A meta-analysis on the relationship between the CAT polymorphism rs1001179 and cancer risk showed a significant association with the risk of prostate cancer." (PMID 32648197, 2021). "Current approaches focus on targeting membrane-associated CAT in cancer cells using antibodies or exogenous singlet oxygen." (PMID 32605023, 2020). "A number of gene nodes linked to drug resistance in other cancer types (including CAT, TRIM59, ANXA2, ADM, AJUBA, HSPA1A/1B, LAMC2, TRIM14, KRT8, KRT18, KRT9, CLDN1, and SMARCA2) were also down-regulated in PARPis-sensitive AsPCs." (PMID 33213473, 2020). "A theoretical investigation of the proposed theory, especially the role of catalase inactivation, can contribute to the understanding of the underlying cause of the anti-cancer effect of CAP." (PMID 33096638, 2020). "Of note, a novel mechanism has linked HNE inactivation of cancer-specific membrane-associated CAT with the subsequent increase of ROS and selective induction of apoptosis in cancer cells." (PMID 31366062, 2019). "Nevertheless, this strategy is still limited by the high operational temperature accompanying the FUS process, which in turn causes the denaturation of CAT and limits further applications for cancer therapy." (PMID 31754380, 2019). "Treatment with MEMCL, at 500 mg/kg, caused significant (p < 0.05) elevation in the level of CAT activity in comparison with the cancer group (Group 2)." (PMID 28872373, 2017). "In summary, this meta-analysis has shown associations of the CAT rs1001179 and rs794316 polymorphisms with an increased cancer risk." (PMID 27449288, 2016). "Accordingly, we conducted a meta-analysis to combine data from all of the available case-control studies in order to validate the association of CAT polymorphisms with cancer risk." (PMID 27449288, 2016). "To obtain a more reliable conclusion, we evaluated the relationship between the two common catalase gene polymorphisms (rs1001179 and rs794316) and cancer risk by a meta-analysis." (PMID 27449288, 2016). "Alterations in both SOD1 and CAT have been implicated in cancer, most likely due to their roles in modulating ROS levels." (PMID 26569310, 2015). "For instance, two potent antioxidant enzymes, catalase and glutathione peroxidase, have been found to be often deficient or have significantly lower activities in cancer tissues than in normal counterparts." (PMID 25436023, 2015).
cancer (continued). "The altered expression of cat (catalase) is associated with oxidative DNA damage and subsequent cancer susceptibility." (PMID 23922661, 2013). "Immunohistochemistry has shown that cancer cells can have elevated levels of antioxidant enzymes, but many of them seem to be deficient in catalase protein or catalase activity." (PMID 22551313, 2012). "The addition of exogenous catalase to ascorbic acid susceptible cancer cell lines neutralizes the cytotoxic effect of ascorbic acid." (PMID 22551313, 2012). "Silenced catalase expression increased the susceptibility of the formerly resistant cancer cell line BT-20 to oxidative stress." (PMID 22551313, 2012). "Higher levels of catalase activity are found in cell lines that are more resistant to oxidative stress than in more susceptible cancer cell lines." (PMID 22551313, 2012). "In the present study we found that extracellular catalase prevented the cell toxic effect of ascorbic acid and supported cell viability of ascorbic acid susceptible cancer cell lines." (PMID 22551313, 2012). "Decreased catalase (CAT) activity is also associated with several cancers." (PMID 36751235, 2023). "Importantly, GLE exhibited chemoprotective activities against cancer, which were associated with promoting antioxidant enzymes, namely CAT and SOD, as well as phase II detoxification enzymes (NQO1 and GSTP1)." (PMID 38104078, 2023). "However, catalase also exhibits tumor-suppressive effects in BC by protecting cells from oxidative damage, preventing DNA damage, and mutations that can contribute to cancer development." (PMID 37513179, 2023). "However, higher catalase levels have been associated with more aggressive cancers when compared to lower CAT concentrations." (PMID 36034648, 2022). "Inspired by this concept, we developed a 5-ALA and CAT co-delivery system based on a theranostic microneedle patch (MN-CCPCA) that forces cancer cell to release the false signal of a “heme deficiency” and thus shuts down the outflow of PpIX through the cascaded downregulation of HIF-1α and FECH." (PMID 36266306, 2022). "Although, extracellular Catalase has been linked with transformation of cancer cells and characterization of purified Catalase from Drosophila suggested a significant fraction may be membrane bound." (PMID 35522719, 2022). "However, CAT overexpression is associated with a significant increase in anchorage-independent proliferation, a hallmark of the aggressive cancer phenotype, and enhanced capacity for self-renewal." (PMID 34943091, 2021). "The mutation of CAT leads to different resistance extents of cancer cells to ROS." (PMID 34721758, 2021). "In the context of plasma oncology, two catalase-dependent apoptotic pathways associated with cancer cells, which possibly could be reactivated by CAP and thus explain the anti-cancer effect of CAP, have been investigated by mathematical modeling." (PMID 34068601, 2021). "Singlet oxygen can inhibit membrane-associated protective catalase on the cancer cells membranes." (PMID 34299530, 2021). "It was observed that reduced CAT activity caused by inflammation in the lungs can lead to an intracellular increase in hydrogen peroxide and the formation of an intracellular environment suitable for DNA damage and cancer promotion." (PMID 32648197, 2021). "In cancer cells, CAT repression has been shown to be linked to hypermethylation of the CpG island in the gene promoter, to histone deacetylation, to the expression of miR-30b, and to the high level of c-abl, which can lead to catalase protein degradation via post-translational modifications." (PMID 34572113, 2021). "Since 1O2 has the capacity to inactivate catalase through reaction with histidine in the active centre of the enzyme, application of plasma to a cancer cell will thus lead to a loss of the protection against the HOCl and ONOO‒ pathway, which causes the cancer cells to undergo apoptosis." (PMID 31810265, 2019).
cancer (continued). "In this respect, in the present study the inclusion of 5% GP in piglets’ diet shows an increase of CAT and GPx activity in colon, a positive aspect in preventing the pathological disorders associated with ROS, such as inflammation and cancer, more common to this segment of the intestinal tract." (PMID 29747456, 2018). "NADPH oxidase (NOX) increases O2∙- levels in cancer cells; therefore, malignant cells may acquire a membrane-associated catalase." (PMID 30260967, 2018). "Similarly, CAT polymorphism has been found to be correlated with several disease entities, including cancer, and metabolic diseases, etc.." (PMID 30225256, 2018). "In conclusion, our results provide evidence that candidate pathogenic genes such as MMP1, CDC45, and CAT and their enriched pathways, respectively, of pathway in cancer, cell cycle, and methane metabolism might be involved in the pathogenesis of CC." (PMID 27034707, 2016). "It was reported that MnSOD2, GPX, and CAT gene polymorphisms decrease the enzymatic activity and therefore may increase the risk of cancer by inducing oxidative DNA damage." (PMID 26823947, 2016). "Our results suggest that therapies aimed at diminishing activities of superoxide dismutase or catalase, could selectively increase the mutational load in ssDNA of actively replicating cancer cells, overloaded with ROS." (PMID 23925127, 2013). "In addition, ascorbic acid resistant cancer cell lines are more able to protect themselves with increased catalase enzymatic activity, in contrast to ascorbic acid susceptible cancer cell lines." (PMID 22551313, 2012). "Notably, high CAT levels have been observed in healthy people, suggesting that dysregulated ROS levels may cause DNA damage and cancer development." (PMID 40722961, 2025). "Furthermore, it is necessary to consider that inhibiting CAT, GPx4, Prxs, TrxR, and other antioxidant enzymes can cause adverse reactions in other organs and tissues, which hinders their widespread application in human cancer." (PMID 38891864, 2024). "Thus, targeting CAT may be a promising therapeutic approach to treat various diseases, including cancer and intestinal dysfunctions caused by the imbalance of the intracellular H2O2 level." (PMID 35453573, 2022). "Thus, CAP may be used as a source of external so-called “primary” singlet oxygen to inactivate the protective membrane-associated catalase in cancer cells." (PMID 33096638, 2020). "Indeed, studies show that membrane-associated catalase is crucial for cancer cell progression." (PMID 31810265, 2019). "Importantly, factors associated with ROS detoxification (and presumptively β-lap resistance) such as catalase expression are deficient in cancer cells relative to normal tissue, further enhancing the potential therapeutic margin of this strategy in specific cancers." (PMID 30318513, 2018). "Thus, those cancer cells that are most susceptible may have an increased expression of peroxiporin in addition to a lower relative catalase activity compared to normal cells." (PMID 28107421, 2017). "Low CAT activity resulting from genetic variations in the CAT enzyme could alter ROS detoxification and increase oxidative stress, implicating oxidative DNA damage and thus increased risk of cancer among younger individuals." (PMID 25837767, 2015). "ATP5α, a highly abundant mitochondrial protein with roles in cancer, was selected to study the unique functions of CAT-tailed forms." (PMID 38798583, 2026). "Its inhibition disrupts oxidative balance, leading to oxidative stress and cell death, which positions catalase as a promising therapeutic target for cancer treatment." (PMID 41699683, 2026). "Consistent with the systemic findings, catalase activity was markedly decreased in PAT of cancer patients compared to the control group (p < 0.0001)." (PMID 41596358, 2026).
cancer (continued). "This review offers a thorough discussion about various nanozymes involved in anti-cancer immunity, including those mimicking catalase (CAT), superoxide dismutase (SOD), peroxidase (POD), and oxidase (OXD)." (PMID 40072370, 2025). "Nanozymes that mimic CAT activity have been recognized as therapeutic sensitizers in cancer treatments, particularly immunotherapy." (PMID 40072370, 2025). "Genes such as FDX1, CAT, CDKN2A, DLAT, LIPT1, and COMMD1, which are associated with cuproptosis, are crucial for the growth, advancement, and spread of various cancers." (PMID 40109870, 2025). "The toxicity of decomposition products to cancer and non-cancer cells was highest for the CAT complexes." (PMID 39940763, 2025). "To mitigate this, we focused on assessing mRNA levels of key antioxidant enzymes (NFE2L2, HMOX1, SOD2, CAT) in both thyroid normal and cancer cells to gain insight into their oxidative stress response ability." (PMID 40927570, 2025). "In the occurrence of cancer, CAT is related to the cellular oxidative stress response, can inhibit the activation of NF-κB, and promote cell apoptosis." (PMID 41305721, 2025). "In pathological contexts such as cancer or persistent oxidative stress, γ-oryzanol downregulates redox enzymes, most notably catalase (CAT), glutathione peroxidase (GPX), and superoxide dismutase (SOD)." (PMID 41009004, 2025). "Catalase (CAT) can form oxygen in malignant tumors by catalyzing endogenous hydrogen peroxide (H2O2; ≈50 × 10−6 to 100 × 10−6 mM), which offers an attractive method for overcoming hypoxia caused by tumors." (PMID 40051791, 2025). "From the gills and liver of fish, cancer prevention agent proteins, such as CAT, GSH, POD and SOD, were isolated to examine biochemical parameters." (PMID 41020660, 2025). "Earlier, researchers have shown that quercetin inhibited overexpression of SOD, CAT, and Nrf2 engineered via redox‐mediated mechanisms and reversed cDDP resistance in cancer cells while it enhanced the expression of these enzymes in normal cells." (PMID 40801052, 2025). "Co-treatment significantly reduced catalase (CAT) activity in both cancer cells compared to the control group and cells treated with each monotherapy." (PMID 39774458, 2025). "After actively targeting vascular cell adhesion molecule-1 (VCAM-1) in cancer cells mediated by macrophage membrane coating, M@GOx-CAT@CuS NPs released GOx and CAT under near-infrared irradiation." (PMID 38840654, 2024). "On the other hand, the optimized antioxidant defense system in cancer cells such as Catalase makes them resistant to internal-originated oxidative storms." (PMID 38600497, 2024). "Polyphenols induce differential expression of antioxidant enzymes such as catalase and superoxide dismutase in cancer cells and normal cells, respectively." (PMID 39204317, 2024). "The key role of hydrogen peroxide in cancer cell damage following intravenous administration of ascorbate was confirmed by the addition of the hydrogen peroxide converting enzyme catalase to the studied system." (PMID 38483584, 2024). "CAT is overexpressed in multiple cancer types, including gastric cancer, colon cancer, melanoma, and leukemia." (PMID 39090114, 2024). "The reduction of catalase gene expression confirmed the pro-oxidant effect of nanoparticles in cancer cells treated at concentrations of 20 and 40 μg/mL." (PMID 38600497, 2024). "Higher levels of catalase can confer resistance to oxidative stress, protect cancer cells from ROS-induced damage, and promote cell survival and proliferation." (PMID 39170262, 2024). "In contrast, pharmacologic inhibition of CAT induces apoptosis in cancer cell lines, such as lung and ovarian cancer." (PMID 39090114, 2024). "The same effect was produced by overexpressing catalase in RasV12DlgRNAi 4DP-fed larvae, thus allowing to establish a relationship between PLP deficiency, CABs, and cancer." (PMID 38830901, 2024).